MARCO (macrophage receptor with collagenous structure)
Diseases named in the same sentence as MARCO in open-access papers (continued):
Sharing a sentence is not in itself a finding about the gene and the disease.
pneumococcal pneumonia (2 papers, 2011 to 2021). A febrile disease caused by STREPTOCOCCUS PNEUMONIAE. "The scavenger receptor MARCO plays an important role in host defense against pneumococcal pneumonia." (PMID 33828999, 2021). "The antioxidant sulforaphane enhances MARCO expression and thereby improves pneumococcal clearance and host survival during secondary pneumococcal pneumonia." (PMID 33828999, 2021). "MARCO is involved in defence against pneumococcal pneumonia." (PMID 21299846, 2011). "Furthermore, MARCO is required for lung defence against pneumococcal pneumonia." (PMID 21299846, 2011).
psoriasis (2 papers, 2020 to 2025). An autoimmune condition characterized by red, well-delineated plaques with silvery scales that are usually on the extensor surfaces and scalp. "It was associated with skin inflammation in the context of psoriasis where MARCO-expressing macrophages were increased compared with normal skin." (PMID 41301909, 2025). "Given its role in macrophage function and association with skin inflammation in conditions such as psoriasis, MARCO may represent a potential diagnostic marker in inflammatory skin diseases like lichen sclerosus." (PMID 41301909, 2025). "On the other hand, the lesional skin of psoriasis possesses heterogeneous CD163+ M2-polarized macrophages, including MARCO+ phenotypes of M2 macrophages, as well as IL-23- or TNFa-producing macrophages that contribute to the Th17-polarized inflammatory microenvironment of psoriasis." (PMID 32707850, 2020).
renal carcinoma (2 papers, 2021 to 2025). A carcinoma arising from the epithelium of the renal parenchyma or the renal pelvis. "The results of the analysis showed that low expression in CD8+ T cells and DCs was linked to a high abundance of MARCO+ TAMs in renal cancer tissue." (PMID 41117057, 2025).
stress incontinence (2 papers, 2024 to 2025). "Macrophage receptors with a collagenous structure (MARCO) are biologically plausible biomarkers associated with stress incontinence, given their roles in smooth muscle contraction." (PMID 40731901, 2025). "In this GWAS, we also observed an association between the genus Acinetobacter and the MARCO gene (β = −0.183, P = 3.67 × 10−6), which encoded macrophage receptor with collagenous structure and correlated with stress urinary incontinence (replication P = 0.003) in a GWAS of European women." (PMID 39513726, 2024).
systemic sclerosis (2 papers, 2023 to 2024). A chronic disorder, possibly autoimmune, marked by excessive production of collagen which results in hardening and thickening of body tissues. "Moreover, research shows that the MARCO+ macrophage subpopulation is associated with driving the onset and progression of diffuse cutaneous systemic sclerosis (SSc), and MARCO+ monocyte-derived macrophages are potent effector cells causing tissue fibrosis." (PMID 37545490, 2023).
triple-negative breast carcinoma (2 papers, 2025). An invasive breast carcinoma which is negative for expression of estrogen receptor (ER), progesterone receptor (PR), and human epidermal growth factor receptor 2 (HER2). "Further research has discovered that SEs can activate the expression of “tumor-specific transcript” MARCO-TST in triple-negative breast cancer, and for the first time confirmed that BET inhibitors can be a potential treatment option for patients with triple-negative breast cancer." (PMID 40672386, 2025). "Multiplex immunofluorescence (m-IF) analysis of human triple-negative breast cancer (TNBC) tissues demonstrated co-localization of MARCO with CD11b+ CD14+ cells that were negative for CD68 expression, suggesting potential expression of MARCO on M-MDSCs." (PMID 40695812, 2025).
allergic asthma (1 paper, 2014). A asthma with a basis in a pathological type I hypersensitivity reaction. "Granucci and colleagues have shown that MARCO mediates cytoskeletal rearrangements promoting dendritic lamellopodia, a finding that is in line with later studies showing MARCO inhibits DC migration, with pathophysiological consequences on allergic asthma and cancer immunotherapy." (PMID 25089703, 2014).
bacteremia (1 paper, 2018). "However, infected Ghrh−/− mice exhibited a dispersed MARCO distribution in the MZ, which can be related to the failure of bacterial clearance and bacteremia development in Ghrh−/− mice when they are infected by a sublethal dose with S. pneumoniae." (PMID 30333823, 2018).
bacterial meningitis (1 paper, 2011). Inflammation of the membranes surrounding the brain and spinal cord due to a bacterial infection. "In order to validate our previous in vitro findings in vivo, we used double fluorescence microscopy with receptor specific antibodies to examine the localization of MARCO and GFAP in astrocytes from infant rats with bacterial meningitis with NM or SP." (PMID 21299846, 2011).
bacterial pneumonia (1 paper, 2021). Acute infection of the lung parenchyma caused by bacteria (e.g., Streptococcus pneumoniae, Haemophilus influenzae, Chlamydia pneumoniae, Mycoplasma pneumoniae, and Legionella pneumophila). "Immunomodulation of MARCO could improve host defense and resistance to secondary bacterial pneumonia." (PMID 34572315, 2021).
bronchiolitis (1 paper, 2021). Inflammation of the bronchioles characterized by swelling of the bronchioles and mucus accumulation. "Using the MARCO rs1318645 TaqMAMA-specific real-time PCR, the outcome of this study is to determine a correlation between MARCO rs1318645 SNP and incidence of bronchiolitis, RSV susceptibility." (PMID 34386467, 2021). "Our finding allowed us to identify a biologically plausible bronchiolitis susceptibility gene candidate: MARCO." (PMID 34386467, 2021).
cerebral infarction (1 paper, 2023). An ischemic condition of the brain, producing a persistent focal neurological deficit in the area of distribution of the cerebral arteries. "However, clearance of HMGB1 released after cerebral infarction may be partially dependent on the involvement of MSR1 or MARCO, and further studies are warranted to understand the mechanism of removal of HMGB1 released after cerebral infarction." (PMID 37062906, 2023).
Chagas disease (1 paper, 2025). A parasitic infection caused by Trypanosoma cruzi. "To evaluate if MARCO was a common identification in the context of other infectious diseases, we searched for it on proteomic data sets from patients with malaria and Chagas disease that were recovered using a similar approach and also in the available Vesiclepedia dataset." (PMID 40565155, 2025). "Nevertheless, MARCO was also not found in plasma EVs from patients with Chagas disease or malaria using the same EV recovery methods." (PMID 40565155, 2025).
fungal keratitis (1 paper, 2022). "Therefore, the upregulated expression of SPDEF and MARCO in murine fungal keratitis and their related properties may serve as potential therapeutic targets in fungal keratitis." (PMID 35743555, 2022).
graft versus host disease (1 paper, 2025). An immune system disorder that occurs after allogeneic hematopoietic stem cell transplant and is a reaction of donor immune cells against host tissues. "Multiplex immunohistochemistry revealed increased numbers of S1PR2+CD45+CD68+FCN1+ inflammatory macrophages and S1PR2+CD45+CD68+MARCO+ Kupffer cells in liver tissues showing ductopenia due to graft-versus-host disease and rejection post-liver transplant compared with normal liver." (PMID 39854311, 2025).
Insulin resistance (1 paper, 2018). Increased resistance towards insulin, that is, diminished effectiveness of insulin in reducing blood glucose levels. "MSR1 and MARCO sense lipoproteins that have been implicated in cardiovascular disease, but the roles for different Class A scavenger receptors in carbohydrate metabolism and insulin resistance are ill‐defined." (PMID 30485705, 2018). "Our results build on this previous work by showing that MSR1 provides a unique protection from excessive insulin resistance compared to other Class A scavenger receptors, since MARCO was dispensable for changes in insulin sensitivity in obese mice." (PMID 30485705, 2018).
kidney cancer (1 paper, 2022). Primary or metastatic malignant neoplasm involving the kidney. "FN1+ TAM highly expressed fibronectin 1 (FN1) and scavenger receptor MARCO, which has been previously reported as a specific macrophage subset in kidney cancer." (PMID 36423636, 2022).
leishmaniasis (1 paper, 2025). Infectious disease that is transmitted through the bite of hematophagous female phlebotomine sand flies. "Considering that Leishmaniasis in Portugal is a zoonotic disease, dogs being the natural reservoir, it was also evaluated if MARCO was identified in plasma EVs from dogs with Canine Leishmaniosis from a previous proteomic study using the same EVs recovery approach." (PMID 40565155, 2025).
lichen sclerosus (1 paper, 2025). "CCL27, along with MARCO, was among the most upregulated genes identified in lichen sclerosus." (PMID 41301909, 2025).
liver fibrosis (1 paper, 2026). "The macrophage receptor with collagenous structure (MARCO) protein is a scavenger receptor expressed by specific subsets of macrophages, and its role in liver fibrosis is unclear." (PMID 41869728, 2026). "Therefore, MARCO+ macrophages have a tissue restorative role in the liver and attenuate fibrogenesis through interaction with HSCs, thereby providing a potential therapeutic pathway for liver fibrosis." (PMID 41869728, 2026). "Adoptive transfer of MARCO+ macrophages in a mouse model of liver fibrosis reduced the expression of extracellular matrix-associated (ECM-associated) genes in hepatic stellate cells (HSCs) and reduced collagen deposition, which did not occur with the transfer of MARCO- macrophages." (PMID 41869728, 2026).
malaria (1 paper, 2025). Malaria is a serious and sometimes fatal disease caused by a parasite that commonly infects a certain type of mosquito which feeds on humans. "No peptide identifications consistent with MARCO were present in malaria and Chagas patients and only one study reported the identification of MARCO in Vesiclepedia." (PMID 40565155, 2025).
malignant glioma (1 paper, 2020). A grade III or grade IV glioma arising from the central nervous system. "Furthermore, both MARCO and CCL7 promoted the upregulation of tafazzin (TAZ), which has been suggested as a key transcriptional coactivator regulating mesenchymal trans-differentiation in malignant gliomas." (PMID 32847614, 2020).
meningococcal meningitis (1 paper, 2011). "In this study we examined the time-dependent expression and co-localization of MARCO to glial cells in a model of experimental pneumococcal and meningococcal meningitis via fluorescence microscopy and using real-time RT-PCR studies of primary rat glia cells." (PMID 21299846, 2011). "We have been able to show a strong increase of MARCO in meningococcal meningitis co-localized to astrocytes." (PMID 21299846, 2011). "Using an infant rat model of experimental pneumococcal and meningococcal meningitis and a primary glia cell culture, our results show a strong increase of MARCO expression after NM infection in astrocytes but not in microglia." (PMID 21299846, 2011).
metastatic tumors (1 paper, 2022). "Most of the macrophage clusters were enriched in primary and/or metastatic tumors, except for a MARCO+ macrophage cluster (C5) enriched in NTL." (PMID 35933472, 2022).
Morton Neuroma (1 paper, 2025). Swelling and inflammation of the nerve between the ends of the metatarsal bones at the base of the toes. "Targeted immunofluorescent analyses confirmed higher densities of intraneural CD163+MARCO+ macrophage subsets in Morton's neuroma." (PMID 39588776, 2025).
neuroborreliosis (1 paper, 2018). "Future experiments are required to confirm the expression of MARCO in microglia in the rhesus macaque model of neuroborreliosis, and its function in B. burgdorferi clearance in non-murine models." (PMID 29922241, 2018).
neuropathic pain (1 paper, 2025). Chronic pain caused by damage to nerve fibers. "There is clear evidence for an ongoing role of the immune system in chronic peripheral neuropathic pain in humans, with macrophages and specifically the M(GC) MARCO+ subset implicated." (PMID 39588776, 2025).
oropharyngeal cancer (1 paper, 2023). Carcinoma, predominantly squamous cell, arising from the epithelial cells of the oropharynx. "Most of the oral and oropharyngeal cancer samples were unmethylated in almost all the investigated gene promoters: EDARADD, GBP4, HAVCR2, HLA DPB1, IL12RB1, MARCO, and SIGLEC12." (PMID 37175405, 2023).
pancreatic ductal adenocarcinoma (1 paper, 2025). An infiltrating adenocarcinoma that arises from the epithelial cells of the pancreas. "While recent studies have demonstrated that pancreatic ductal adenocarcinoma (PDAC)-conditioned MARCO+ macrophages exhibit MDSC-like characteristics, the precise expression profile and functional significance of MARCO in MDSCs remain incompletely characterized." (PMID 40695812, 2025).
parasite infection (1 paper, 2018). "While some evidence supports the involvement of SR-AI and MARCO in parasite infection (Schistosoma japonicum and Leishmania major, respectively), the ability of SR-AI to directly recognize helminth components has only been shown for Heligmosomoides polygyrus calreticulin." (PMID 30500820, 2018).
Parkinson disease (1 paper, 2022). A progressive degenerative disorder of the central nervous system characterized by loss of dopamine producing neurons in the substantia nigra and the presence of Lewy bodies in the substantia nigra and locus coeruleus. "Interesting, CXCL5 and MARCO are both related to inflammation, while UCHL1 is a gene specific for Parkinson’s disease but also described in AD." (PMID 36012501, 2022).
Respiratory tract infection (1 paper, 2021). An infection of the upper or lower respiratory tract. "We hypothesize the immune system impairment on the epithelial barrier, in which MARCO is involved, predisposing to respiratory tract infections and recurrent wheezing in the first years of life." (PMID 34386467, 2021).
sarcoma (1 paper, 2021). A usually aggressive malignant neoplasm of the soft tissue or bone. "Additionally, the expression of MARCO in sarcoma, squamous carcinoma of the head and neck, and thoracic cancer does not change significantly." (PMID 34778091, 2021). "Additionally, the expression of MARCO in sarcoma, squamous carcinoma of the head and neck, and thoracic cancer did not change significantly." (PMID 34778091, 2021).
silicosis (1 paper, 2020). Silicosis is a respiratory disease caused by breathing in (inhaling) silica dust. "Environmental particles like titanium dioxide (TiO2) have been described to be bound and phagocytosed by macrophage receptor with collagenous structure (MARCO, also known as SR-A6 or SCARA2), which is important in models of silicosis." (PMID 33363539, 2020).
Stroke (1 paper, 2018). Sudden impairment of blood flow to a part of the brain due to occlusion or rupture of an artery to the brain. "Increased capture of Dextran-FITC associated with MARCO+ MZM was observed 2 days after experimental stroke in comparison to sham-operated and naïve controls." (PMID 29872438, 2018). "This could relate to the increased density of MARCO+ MZM present after experimental stroke." (PMID 29872438, 2018). "However, image analysis showed LAMP2 co-localization was significantly increased in both F4/80hi CD11b−/lo and F4/80+ CD11b+ subsets of RPM and MARCO+ MZM 2 days after experimental stroke." (PMID 29872438, 2018). "Similarly to RPM, absolute numbers of MARCO+ and MOMA-1+ macrophage subsets were reduced 2 days after experimental stroke in comparison to sham-operated animals." (PMID 29872438, 2018). "However, expression of MHC Class II on MARCO+ MZM (red) and both populations of RPM (F4/80; blue, CD11b; blue) appeared reduced 1–7 days after experimental stroke." (PMID 29872438, 2018).
synovitis (1 paper, 2023). Inflammation of a synovial membrane. "MARCO, an M1 macrophage marker, was reported to be significantly associated with early synovitis and the process of including increased trafficking and migration of monocytes into the synovial membrane." (PMID 35473522, 2023).
TB meningitis (1 paper, 2017). "A recent study revealed two SNPs of MARCO, rs2278589 and rs6751745, were associated with PTB but not with TB meningitis (TBM)." (PMID 28693442, 2017).
vitiligo (1 paper, 2021). Generalized well circumscribed patches of leukoderma that are generally distributed over symmetric body locations and is due to autoimmune destruction of melanocytes. "The upregulated genes in vitiligo lesional skin include markers of inflammation (such as MARCO, NLRP10, PTGS2, and IL36G), oxidative response genes (DUOXA2), and NK cell receptors (NCR3LG1), revealing presence of activated immune response in vitiligo lesions." (PMID 33815367, 2021).